FBP1 (fructose-bisphosphatase 1)
Diseases named in the same sentence as FBP1 in open-access papers (continued):
Sharing a sentence is not in itself a finding about the gene and the disease.
osteosarcoma (5 papers, 2021 to 2025). A usually aggressive malignant bone-forming mesenchymal neoplasm, predominantly affecting adolescents and young adults. "We screened out the promising hypoxia genes SLC2A1 and FBP1 in osteosarcoma, and the patient risk score based on gene expression is related to the degree of tumor infiltration of multiple immune cells." (PMID 36316355, 2022). "This study used multivariate COX regression analysis to select the hypoxia genes SLC2A1 and FBP1 in patients with osteosarcoma, and used the expression of these two genes to divide the patients with osteosarcoma into high-risk and low-risk groups." (PMID 36316355, 2022). "In summary, our study unveils TRIM47 as a bona fide activator of the Wnt/β‐catenin pathway to facilitate osteosarcoma tumourigenesis and progression via ubiquitinating FBP1 protein." (PMID 40801794, 2025). "In osteosarcoma cells, we demonstrated that FBP1 physically binds with EZH2 and that a positive mutual regulatory mechanism exists between FBP1 and EZH2." (PMID 36000567, 2022). "In osteosarcoma, glucose deficiency enhances the expression of lncRNA HAND2-AS1, which binds to Fructose-1, 6-bisphosphatase 1 (FBP1) to sequester the interaction between FBP1 and HIF1α mRNA, thereby influencing glycolysis-related genes." (PMID 35625948, 2022). "This study constructed a prognostic model based on hypoxia-related genes SLC2A1 and FBP1 in patients with osteosarcoma, and explored their correlation with immune cells, inflammatory markers and ferroptosis-related genes." (PMID 36316355, 2022). "Another study has shown that HAND2-AS1 regulates osteosarcoma metabolism via sequestering fructose-1,6-bisphosphatase 1 (FBP1) from binding to HIF1α thereby increasing the HIF1α expression." (PMID 33652661, 2021). "Therefore, in this study, we first screened two prognostic-related hypoxia genes, Solute Carrier Family 2 Member 1 (SLC2A1) and Fructose-Bisphosphatase 1 (FBP1), in osteosarcoma." (PMID 36316355, 2022). "Therefore, in this study, we constructed a prognostic model based on hypoxia-related genes SLC2A1 and FBP1 in patients with osteosarcoma, and explored its correlation with immune cells, inflammatory markers and ferroptosis-related genes." (PMID 36316355, 2022). "This suggests that SLC2A1 and FBP1 are promising research targets in osteosarcoma." (PMID 36316355, 2022). "This indicates that SLC2A1 and FBP1 are promising targets for osteosarcoma research." (PMID 36316355, 2022). "The results of univariate Cox regression analysis showed SLC2A1, ENO1, FBP1 and PGM1, while multivariate COX regression analysis showed that SLC2A1 and FBP1 could indicate the prognostic risk of patients in osteosarcoma." (PMID 36316355, 2022). "Therefore, in this study, we screened out the hypoxia genes SLC2A1 and FBP1 in patients with osteosarcoma through multivariate COX regression analysis, and used the expression of these two genes to divide patients with osteosarcoma into high-risk and low-risk groups." (PMID 36316355, 2022). "Mechanistically, TRIM47 reduced the protein stability of fructose 1, 6‐bisphosphatase 1 (FBP1), thereby triggering the activation of the Wnt/β‐catenin pathway, ultimately leading to tumorigenesis and progression of osteosarcoma." (PMID 40801794, 2025). "In osteosarcoma, we constructed a prognostic model for SLC2A1 and FBP1, and the prognosis of the patient can be predicted based on the risk score of expression." (PMID 36316355, 2022). "Furthermore, we analyzed the relationship between FBP1 and EZH2 in OC based on TCGA cohorts, and we confirmed a positive correlation between FBP1 and EZH2 in osteosarcoma cells." (PMID 36000567, 2022).
triple-negative breast carcinoma (5 papers, 2017 to 2022). An invasive breast carcinoma which is negative for expression of estrogen receptor (ER), progesterone receptor (PR), and human epidermal growth factor receptor 2 (HER2). "ALDOA regulates FBP levels during glycolysis and the upstream enzyme FBP1 is linked to progression of triple-negative breast cancer cells." (PMID 36077431, 2022). "In this light, a recent report regarding Snail-mediated suppression of fructose-1,6-bisphosphatase (FBP1) in triple-negative breast cancer is of special interest because loss of FBP1 suppresses endergonic gluconeogenesis from F1,6BP to F6P that is the reverse enzymatic reaction of PFK-1." (PMID 32487689, 2020).
leukemia (4 papers, 2018 to 2025). A malignant (clonal) hematologic disorder, involving hematopoietic stem cells and characterized by the presence of primitive or atypical myeloid or lymphoid cells in the bone marrow and the blood. "FBP1 inhibition ameliorates chemotherapy resistance in Evi1 upregulated leukemia patients by reducing oxidative phosphorylation (OXPHOS)." (PMID 40100307, 2025). "The transcriptional upregulation of Fbp1 and the catalase-activated pentose phosphate pathway are critical for the progression of Evi1-driven leukemias." (PMID 40100307, 2025). "Together, these findings imply that inhibiting FBP1 may increase chemotherapy sensitivity in individuals with Evi1-high leukemia by reducing OXPHOS." (PMID 40100307, 2025). "FBP1-overexpressing blasts may initiate leukemia cell death by activating mitochondrial reprogramming in AML cells, supporting the therapeutic contribution of FBP1-based drugs for AML treatment." (PMID 37296673, 2023). "Therefore, the therapeutic role of vitamin-D-induced FBP1 overexpression in leukemia remains a viable option that should be further explored." (PMID 36232688, 2022). "Thus, targeting FBP1 in highly Evi1-overexpressing leukemias may be an ideal therapeutic approach." (PMID 40100307, 2025). "Five of the top metabolic genes upregulated in leukemia when compared to CD8+ T cells were Hmgcs2, Chdh, Fbp1, Prodh, and Ldhb." (PMID 30140438, 2018).
nasopharyngeal carcinoma (4 papers, 2021 to 2025). A carcinoma arising from the nasopharyngeal epithelium. "Compared to normal nasopharyngeal epithelial cells, nasopharyngeal cancer cells exhibit decreased levels of FBP1 expression." (PMID 40100307, 2025). "It is also interesting that FBP1 was found to enhance radiosensitivity in nasopharyngeal carcinoma cells." (PMID 35477823, 2022). "In nasopharyngeal carcinoma cells, fructose-1,6-bisphosphatase 1 (FBP1) was found to suppress the autoubiquitylation of FBXW7 to restrained mTOR-glycolysis signals and promote radiation-induced apoptosis and DNA damage." (PMID 34760892, 2021).
steatosis (4 papers, 2021 to 2025). Increased lipid within the cytoplasm of cells. "It enhances insulin sensitivity, reduces liver injury and steatosis, and inhibits key hepatic enzymes and transcription factors such as G6Pase, FBP-1, and SREBP1, which are crucial in gluconeogenesis and lipogenesis." (PMID 40689212, 2025). "Disruption of the fbp1 gene in mice alters liver metabolic homeostasis and supports tumorigenesis, and eventually develop hepatomegaly and steatosis." (PMID 39036704, 2024). "FBP1 deletion leads to steatosis, accompanied by the activation and senescence of hepatic stellate cells, which show senescence-related secretory phenotypes." (PMID 34496868, 2021).
glioblastoma (3 papers, 2021 to 2025). The most malignant astrocytic tumor (WHO grade IV). "Fructose 1,6-bisphosphatase 1 (FBP1) has been considered as a potential prognostic biomarker in glioblastoma (GBM), and this study explored the underlying mechanism." (PMID 39902328, 2025). "When FBP1 was downregulated, glycolysis increased, and the decrease in FBP1 level reprogrammed the metabolism of glioblastoma cells." (PMID 33564363, 2021). "In glioblastoma (GBM) cells treated with ionizing radiation (IR), fructose 1,6-bisphosphatase 1 (FBP1) is downregulated, along with increased glucose uptake and extracellular acidification, indicating increased intracellular glycolysis." (PMID 35637953, 2022).
Insulin resistance (3 papers, 2021 to 2023). Increased resistance towards insulin, that is, diminished effectiveness of insulin in reducing blood glucose levels. "According to the literature, FBP1 is involved in the negative regulation of appetite and of adiposity, and it prevents the development of insulin resistance." (PMID 35457071, 2022). "Taken together, our data indicated that 1α,25(OH)2D3/FBP1 signaling could regulate the inflammation of γδ T cells to alleviate insulin resistance in obese mice." (PMID 37908738, 2023). "In LW, animals are probably more starved than in EW, which could explain the reduced expression of FBP1 and further explain the transient settlement of insulin resistance in LW." (PMID 35457071, 2022).
kidney cancer (3 papers, 2020 to 2022). Primary or metastatic malignant neoplasm involving the kidney. "To investigate the expression patterns of FBP1 in kidney cancer, we analyzed the mRNA-seq datasets of 611 RCC and normal renal control samples from the TCGA database." (PMID 35978816, 2022). "Given that FBP1 is downregulated in RCC as a tumor suppressor and that its depletion enhances HIF activity to suppress kidney cancer, we want to investigate the underlying molecular mechanism of Warburg effect in RCC through FBP1." (PMID 35978816, 2022). "Previous studies have shown that FBP1 could inhibit glycolysis in kidney cancer, and the expression of FBP1was significantly lower in patients with high-grade ccRCC than in patients with low-grade ccRCC." (PMID 33564363, 2021). "It has been confirmed that fructose-1,6-bisphosphatase (FBP1) can bind to the inhibitory domain of HIF-1α and restrict the growth of kidney cancer by inhibiting glycolysis." (PMID 32928258, 2020).
melanoma (3 papers, 2022 to 2025). A malignant, usually aggressive tumor composed of atypical, neoplastic melanocytes. "In conclusion, we reported the association of HRGs with patient prognosis in melanoma and screened for novel gene signatures, including FBP1, NDRG1, GPI, IER3, B4GALNT2, BGN, PKP1, and EDN2." (PMID 37422626, 2023).
ovarian tumor (3 papers, 2021 to 2022). "First, we observed that downregulation of FBP1 was prevalent in ovarian tumor tissues and was associated with poor prognosis." (PMID 34363022, 2021). "This study found that the expression levels of the glycolytic genes DCN and FBP1 positively correlated with the ovarian tumor microenvironment's immune score." (PMID 34496868, 2021). "Based on these data, the promoting effect of FBP1 on ovarian tumor formation and cisplatin resistance may be attributed to the up-regulation of the EZH2/H3k27me3 signaling pathway." (PMID 36000567, 2022).
acute liver failure (2 papers, 2021 to 2023). Rapid deterioration of liver function causing encephalopathy and coagulopathy. "Serum levels of FBP1 have been shown to be of prognostic value in acute liver failure associated with 30-day survival in end-stage liver disease." (PMID 36869085, 2023). "Wang et al13 suggested that Fbp1 is a promising biomarker of acute liver failure, as high serum levels of Fbp1 were found to be correlated with high mortality." (PMID 33960626, 2021).
acute promyelocytic leukemia (2 papers, 2022). An aggressive form of acute myeloid leukemia (AML), characterized by arrest of leukocyte differentiation at the promyelocyte stage, due to a specific chromosomal translocation t(15;17) in myeloid cells. "In addition to MV4–11/MOLM-14, significant elevation of FBP1 and induction of blast differentiation could be observed in 1,25VD3 treatment of HL60, a human acute promyelocytic leukemia (APL) cell line (Supple." (PMID 35366947, 2022). "We recently discovered that vitamin D treatment in vitro significantly induced both FBP1 gene and protein expression intracellularly in various leukemic cell lines, including MV4-11, MOLM-14, and HL60 (a human acute promyelocytic leukemia (APL) cell line)." (PMID 36232688, 2022).
adenocarcinomas of the prostate (2 papers, 2008 to 2020). "Expression of FBP1 and FBP3 was detectable in luminal epithelia of normal glands, prostatic intraepithelial neoplasia (PIN) as well as adenocarcinomas of the prostate." (PMID 19087307, 2008).
allergic asthma (2 papers, 2021 to 2023). A asthma with a basis in a pathological type I hypersensitivity reaction. "In conclusion, we showed that Fbp1 expression was increased in the bronchial epithelial cells of a murine model of allergic asthma." (PMID 33960626, 2021).
allergic disease (2 papers, 2021 to 2024). An immune response that occurs following re-exposure to an innocuous antigen, and that requires the presence of existing antibodies against that antigen. "However, the expression and function of Fbp1 have not been investigated in allergic diseases such as asthma." (PMID 33960626, 2021).
asthma (2 papers, 2021 to 2024). "Furthermore, we sought to examine the mechanisms underlying the effects of Fbp1 on oxidative stress‐induced apoptosis in asthma." (PMID 33960626, 2021). "Fbp1 can aggravate oxidative stress-induced apoptosis by suppressing Nrf2 signaling, which exerts a significant impact on the prevalence and severity of asthma." (PMID 38699230, 2024). "Gene Expression Omnibus (GEO) data sets revealed that Fbp1 was overexpressed in a murine model of asthma and in interleukin (IL)‐4‐ or IL‐13‐stimulated bronchial epithelial cells." (PMID 33960626, 2021). "Collectively, our data indicate that Fbp1 aggravates oxidative stress‐induced apoptosis by suppressing Nrf2 signalling, substantiating its potential as a novel therapeutic target in asthma." (PMID 33960626, 2021). "In the current study, we aimed to investigate the expression of Fbp1 in a murine model of asthma and interleukin (IL)‐4‐stimulated or IL‐13‐stimulated airway bronchial cell lines." (PMID 33960626, 2021). "Collectively, our results suggest that Fbp1 may be a potential therapeutic target related to bronchial epithelial cell apoptosis and oxidative stress in asthma." (PMID 33960626, 2021). "Overall, these data indicate that the mRNA and protein expression of Fbp1 may be up‐regulated in bronchial epithelial cells in asthma." (PMID 33960626, 2021). "Here, we examined the expression, function and mechanism of action of Fbp1 in asthma." (PMID 33960626, 2021). "This is consistent with our results suggesting that Fbp1 may be involved in the pathogenesis of asthma and that its elevated level in epithelial cells following ovalbumin challenge or IL‐4 or IL‐13 treatment may be a detrimental mechanism inducing injury in bronchial epithelial cells." (PMID 33960626, 2021). "Thus, Fbp1 may be a potential target for improving asthma treatment." (PMID 33960626, 2021). "However, the role of Fbp1 in inflammatory diseases, such as asthma, has not been elucidated." (PMID 33960626, 2021).
atherosclerosis (2 papers, 2021 to 2024). A disease characterized by the build-up of fatty material and calcium deposition in the arterial wall resulting in partial or complete occlusion of the arterial lumen. "This review focuses on the role and mechanism of action of miR-26 in atherosclerosis, including the detection value of miR-26 and the potential development of drugs targeting its downstream genes, such as ACC1/2, COL1A1, CPT1A, FBP1, DGAT2, and SMAD7, to provide insight for drug development." (PMID 38195542, 2024).
esophageal cancer (2 papers, 2021 to 2023). A primary or metastatic malignant neoplasm involving the esophagus. "The abnormal expression or loss of function of FBP1 has been observed in breast and esophageal cancer." (PMID 34496868, 2021). "Furthermore, FBP1 promotes the proliferation, migration, and invasion of esophageal cancer cells by regulating fatty acid metabolism." (PMID 36900384, 2023).
esophageal squamous cell carcinoma (2 papers, 2020 to 2022). Esophageal squamous cell carcinoma (ESCC) is a type of esophageal carcinoma (EC) that can affect any part of the esophagus, but is usually located in the upper or middle third. "Data on FBP1’s role in EAC are still scarce, but a recent study in esophageal squamous cell carcinoma also found the loss of FBP1 being associated with increased proliferation, migration, and invasion." (PMID 35477823, 2022). "In esophageal squamous cell cancer, it has been shown that FBP1 promotes proliferation, migration, and invasion by regulating fatty acid metabolism in in vitro experiments." (PMID 35477823, 2022).
idiopathic nephrotic syndrome (2 papers, 2024 to 2026). Nephrotic syndrome for which no cause has been identified. "In idiopathic nephrotic syndrome, urinary FBP1 activity is elevated during active proteinuria and normalizes following prednisone treatment." (PMID 41481634, 2026).
intrahepatic cholangiocarcinoma (2 papers, 2021 to 2024). A carcinoma that arises from the intrahepatic bile duct epithelium in any site of the intrahepatic biliary tree. "MT1JP inhibited proliferation, migration, invasion and tumorigenesis and enhanced apoptosis in intrahepatic cholangiocarcinoma cells as a miRNA sponge to bind to miR-18a-5p to facilitate the expression of FBP1." (PMID 33557774, 2021).
pancreatic ductal adenocarcinoma (2 papers, 2018 to 2020). An infiltrating adenocarcinoma that arises from the epithelial cells of the pancreas. "Moreover, FBP1 and PD-L1 protein expression were negatively correlated in pancreatic ductal adenocarcinoma (PDAC) specimens from a cohort of patients." (PMID 31938049, 2020).
prostate tumor (2 papers, 2020 to 2022). "Expression of PTEN and FBP1 was analyzed in several PCa cell lines and prostate tumor tissues in mice." (PMID 36237339, 2022).